LGI1 (leucine rich glioma inactivated 1)
Diseases named in the same sentence as LGI1 in open-access papers (continued):
Sharing a sentence is not in itself a finding about the gene and the disease.
encephalitis (continued). "For anti‐LGI1 antibody encephalitis, hyponatremia is common, and some AEDs, such as carbamazepine and oxcarbazepine, may aggravate this condition." (PMID 33683811, 2021). "After exclusion criteria were applied, a total of 185 patients with AE remained, including 79 patients with anti-NMDAR encephalitis, 55 with anti-LGI1 encephalitis, 30 with anti-CASPR2 encephalitis, 16 with anti-GABABR encephalitis, and 5 with anti-AMPAR encephalitis." (PMID 34135845, 2021). "However, in two LGI1-encephalitis cases, final diagnosis of AE was retrospectively confirmed after the introduction of cell-based assay in our laboratory in 2012." (PMID 33767656, 2021). "Dysfunction of temporal cortex and hippocampus may be related to temporal epilepsy and cognitive deficits in anti-LGI1 encephalitis patients." (PMID 34421519, 2021). "Furthermore, patients with anti-LGI1 encephalitis presented with large-scale functional network disruptions, in addition to the hippocampal damage, which contributed to the extra-limbic clinical manifestations." (PMID 34616389, 2021). "In addition to CASPR2 LGI1 encephalitis, further autoantibodies termed GABABR antibodies were reported in 2010 to be associated with memory dysfunction, confusion, behavioral abnormalities, and psychosis." (PMID 33026492, 2021). "Memory impairment in LGI1 patients was related to stronger functional connectivity with the insula brain region, salience network, and default mode network, indicating network-based impairments due to LGI1 encephalitis." (PMID 33026492, 2021). "In a retrospective study in the UK, 77% (20/26) of anti-LGI1 encephalitis patients experienced FBDS prior to the development of limbic encephalitis and found that early immunotherapy for FBDS might prevent progression to cognitive impairment." (PMID 33767656, 2021). "Subtle brachio-facial-dystonic seizures were commonly missed in early anti-LGI1 encephalitis." (PMID 34546417, 2021). "Furthermore, the present study aimed to determine the correlation of the metabolism pattern with the daily activities of anti-LGI1 encephalitis patients." (PMID 34616389, 2021). "Moreover, the previous viewpoint that anti-LGI1 encephalitis is a monophasic disorder has also been challenged; 12.5–35.3% of the patients will undergo at least one relapse after the acute phase." (PMID 34168612, 2021). "However, to the best of our knowledge, there is a paucity of large-sample and long-term follow-up studies assessing overall clinical prognosis in anti-LGI1 encephalitis." (PMID 34168612, 2021). "The clinicopathological basis of this metabolic characteristic of anti-LGI1 encephalitis AE remains unclear." (PMID 34616389, 2021). "Leucine-rich glioma-inactivated protein 1 (LGI1) antibodies are probably the most common cause of limbic encephalitis and the second most common cause of autoimmune encephalitis after anti-N-methyl-D-aspartate receptor (NMDAR) encephalitis." (PMID 34168612, 2021). "In LGI1-antibody encephalitis, the seizure profile is especially well-characterised." (PMID 34108243, 2021). "Patients with anti-LGI1/CASPR2-encephalitis show a much lower median mRS of 1 at 3 months." (PMID 34093529, 2021). "Clinical characteristics of patients with anti-LGI1 encephalitis." (PMID 34168612, 2021). "Furthermore, a recent report suggested that a patient who recovered from LGI1- encephalitis developed a new onset psychotic disorder after surviving a one-year course of LGI1-antibody-positive encephalitis." (PMID 34057596, 2021). "LGI1-antibody encephalitis is most common in the elderly with a significant male preponderance." (PMID 31655889, 2021). "The common left hippocampal abnormalities in patients with anti-LGI1 encephalitis could be partially due to the asymmetric distribution of LGI1 expression in the human brain." (PMID 34616389, 2021).
encephalitis (continued). "Some studies have suggested that effective and long-term immunotherapy could improve the prognosis of anti-LGI1 encephalitis, while the complications of chronic immunotherapy cannot be ignored, as they occurred in approximately one-half of the patients." (PMID 34168612, 2021). "Twenty-one patients (21/48, 44%) with anti-LGI1 encephalitis were examined for ACES scores." (PMID 35095744, 2021). "In this study, we described the clinical characteristics of anti-LGI1 encephalitis." (PMID 34168612, 2021). "Moreover, hippocampal sclerosis due to seizure is commonly observed in both anti‐GABABR 26, 32 and anti‐LGI1 encephalitis in long‐term follow‐ups." (PMID 33683811, 2021). "Thus, optimal form and duration of immunotherapy for anti-LGI1 encephalitis patients remain to be identified." (PMID 34975858, 2021). "Among these, merely one study investigated the topography of certain anti-LGI1 encephalitis." (PMID 34616389, 2021). "Similarly, a study reported that the LGI1-antibody encephalitis affected asymmetrically only one hemisphere, which was contralateral to the affected limb for several months." (PMID 34616389, 2021). "We found that anti-LGI1 encephalitis patients had decreased white matter integrity in the genu, body, and splenium of corpus callosum than controls, leading to the lack of movement coordination, low muscle tone, distorted head or facial features, spasms, and seizures." (PMID 32317923, 2020). "Moreover, gut microbiota are expected to be potential therapeutic targets of anti-LGI1 encephalitis." (PMID 33193049, 2020). "Specific HLA alleles and linked haplotypes have been strongly associated with other neurological neuroimmune diseases such as leucine‐rich glioma‐inactivated 1 (LGI1), contactin‐associated protein‐like 2 (CASPR2) and N‐methyl‐d‐aspartic acid receptor (NMDAR) antibody‐associated encephalitis." (PMID 33425355, 2020). "Cognitive impairment could be seen in most patients with anti-LGI1 encephalitis, and it is often, predominately, memory deterioration." (PMID 33162923, 2020). "The clinical manifestations of anti-LGI1 encephalitis are various." (PMID 33162923, 2020). "Our studies provide evidence of SD in patients with LGI1-Ab encephalitis." (PMID 32849186, 2020). "Much less is known about other variants, namely the anti‐leucine‐rich glioma‐inactivated 1 (LGI1), anti‐gamma aminobutyric acid‐B receptor (GABABR), and anti‐contactin‐associated protein‐like 2 (CASPR2) encephalitis, whose prevalence has been shown to be significant at 30%, 5%, and 3%, respectively." (PMID 32783406, 2020). "Domains of MoCA-B test in patients with anti-LGI1 antibody encephalitis." (PMID 33162923, 2020). "Studies have demonstrated anti‐LGI1 encephalitis to be fairly responsive to immunotherapy." (PMID 32783406, 2020). "Given the fact that the Sphingomonas genera increased in both anti-LGI1 encephalitis and Parkinson's disease, we made a bold assumption that the Sphingomonas may link to the extrapyramidal symptoms or even the pathomechanisms of FBDS." (PMID 33193049, 2020). "We found that 23.8% of patients with LGI1-Ab encephalitis presented SD." (PMID 32849186, 2020). "Demographic and clinical characteristics of patients with anti-LGI1 encephalitis." (PMID 33510707, 2020). "The hypothesis was that we would detect brain connectivity and microstructure differences in anti-LGI1 encephalitis within the cortical-subcortical neural systems that support memory, cognition, and motion dysregulation for anti-LGI1 encephalitis." (PMID 32317923, 2020). "Domains of MMSE test in patients with anti-LGI1 antibody encephalitis." (PMID 33162923, 2020). "We investigated the clinical features and gut microbial alterations of anti-LGI1 encephalitis." (PMID 33193049, 2020). "Encephalitis with LGI1 antibodies occurs when antibodies mistakenly attack LGI1." (PMID 32317923, 2020). "Further studies on members within this genus in anti-LGI1 encephalitis are needed." (PMID 33193049, 2020).
encephalitis (continued). "FBDS is considered a pathognomonic feature of anti‐LGI1 encephalitis." (PMID 32783406, 2020). "In addition, we found reduced functional connectivity in ACC in anti-LGI1 encephalitis patients compared with controls." (PMID 32317923, 2020). "The depletion of these genera may participate in the pathogenesis of anti-LGI1 encephalitis, and microbial metabolites especially SCFAs should be further studied in the disorder." (PMID 33193049, 2020). "Our results suggest that 18F-FDG-PET abnormalities may support the evidence for a clinical diagnosis of subjects with anti-LGI1 encephalitis." (PMID 32581996, 2020). "In this study, the decreased FA in the superior longitudinal fasciculus indicated that the integrity of frontal-parietal network connection was destroyed, which may be the main reason for the significant decline of memory in anti-LGI1 encephalitis patients." (PMID 32317923, 2020). "Interestingly, the cognitive deficits in LGI1 encephalitis can come in isolation and lead to the working diagnosis of a primary neurodegenerative disease such as Alzheimer’s." (PMID 32824982, 2020). "Therefore, when evaluating a movement disorder suggestive of FBDS, the finding of BG lesions should reinforce the suspicion of anti-LGI1 encephalitis." (PMID 33510707, 2020). "In addition, structural magnetic resonance imaging (MRI) studies have revealed decreased volumes of the hippocampus, pallidum, nucleus accumbens, brainstem and cerebellum in patients with anti-LGI1 encephalitis." (PMID 32317923, 2020). "Comparisons of FA maps between patients with anti-LGI1 encephalitis and normal controls." (PMID 32317923, 2020). "BG was another important structure in the pathogenesis of anti-LGI1 encephalitis, which may be involved in the development of FBDS." (PMID 33510707, 2020). "Anti-LGI1 encephalitis has a good response to hormone and other immune system-based therapy." (PMID 33162923, 2020). "LGI1-Ab encephalitis is characterized by limbic system involvements." (PMID 32849186, 2020). "Comparisons of MD maps between patients with anti-LGI1 encephalitis and normal controls." (PMID 32317923, 2020). "Elevation of this phylum in our results may suggest its proinflammatory effects in anti-LGI1 encephalitis." (PMID 33193049, 2020). "In addition, the anti-LGI1 encephalitis patients had a higher abundance of the Proteobacteria phylum, and a lower abundance of the Bacteroidetes and Firmicutes phylum, when compared with HCs." (PMID 33193049, 2020). "The correction of this index may be therapeutic methods or a good prognostic factor in anti-LGI1 encephalitis." (PMID 33193049, 2020). "Twenty-seven patients with LGI1-Ab encephalitis underwent PSG or actigraphy recordings." (PMID 32849186, 2020). "PSG results of patients with LGI1-Ab encephalitis and healthy controls." (PMID 32849186, 2020). "Overload in these certain genera may contribute to the development of anti-LGI1 encephalitis or even link to its specific symptoms." (PMID 33193049, 2020). "Early treatment of anti-LGI1 encephalitis during the "inflammatory activity state" is crucial for overall prognosis and may avoid the development of dementia in some cases." (PMID 32560097, 2020). "Therefore, the aim of this study was to examine the whole-brain functional and structural alterations as well as their correlations with clinical disease severity in encephalitis with LGI1 antibodies using a data-driven, multimodal MRI approach." (PMID 32317923, 2020). "Furthermore, the correlation of the reduced connectivity in hippocampus with disease severity suggests that the hippocampal damage plays an important role in the symptomatology of anti-LGI1 encephalitis." (PMID 32317923, 2020). "There was a significant correlation between anti-LGI1 encephalitis with FDBS and basal ganglia." (PMID 33380947, 2020). "Most patients affected by anti-LGI1 encephalitis are men between the ages of 50 and 70 years." (PMID 33510707, 2020).
encephalitis (continued). "Among them, anti-LGI1 encephalitis is a treatable etiology of AE." (PMID 33162923, 2020). "The MRI features of an anti-LGI1 encephalitis patient in our cohort were presented." (PMID 33193049, 2020). "A few cases have reported pilomotor seizures as the main manifestation of anti-LGI1 encephalitis." (PMID 32153488, 2020). "However, the mechanisms by which these genera act as triggers, promoters, or responsers in the pathogenesis of anti-LGI1 encephalitis are unclear." (PMID 33193049, 2020). "Demographic and clinical characteristics of anti-LGI1 encephalitis patients." (PMID 32317923, 2020). "All patients with LGI1-Ab encephalitis had limbic encephalitis." (PMID 32849186, 2020). "A recent report showed that, compared with other types of AE such as anti-NMDAR encephalitis or LGI1 AE, the rate of seizure remission in anti-GABABR encephalitis after 2 years follow-up was the lowest (55%), indicating the necessity of long-term AED treatment." (PMID 32431657, 2020). "A total of 120 patients were diagnosed with LGI1-Ab encephalitis at PUMCH." (PMID 32849186, 2020). "However, given the marked differences in clinical presentation with AMPAR encephalitis, it is likely that LGI1 antibodies have other downstream effects in addition to modulation of AMPARs." (PMID 32873782, 2020). "Our report emphasizes the possible significance of pilomotor seizures in anti-LGI1 encephalitis." (PMID 32153488, 2020). "FBDS typically precedes the onset of anti-LGI1 encephalitis." (PMID 33510707, 2020). "Anti-LGI1 encephalitis is more common in middle-aged and elderly males (over 50 years of age)." (PMID 33162923, 2020). "Both RBD and PLMS were observed more frequently in patients with LGI1-Ab encephalitis." (PMID 32849186, 2020). "The differences in specific microbial lanscapes between the two AEs indicate that the gut microbiota may be an effective marker for the differential diagnosis of anti-NMDAR encephalitis and anti-LGI1 encephalitis." (PMID 33193049, 2020). "Anti-LGI1 antibody-related encephalitis and anti-CASPR2 antibody-related encephalitis may also be associated with thymoma." (PMID 31781111, 2019). "Such epilepsies are essentially variants of autoimmune encephalitis, including anti-N-methyl-D-aspartate (NMDA)-receptor encephalitis or anti-leucine-rich glioma-inactivated-1 (LGI1) encephalitis, in which autoantibodies for autoantigens elicit excessive inflammation in the brain." (PMID 31185666, 2019). "Among the 111 anti-LGI1 encephalitis patients, 13 patients had ADs, including HT (n = 6), vitiligo (n = 2), anaphylactoid purpura (n = 1), SLE (n = 1), the coexistence of SLE and anaphylactoid purpura (n = 1), Sjögren's syndrome (SS) (n = 1), and uveitis (n = 1)." (PMID 31736858, 2019). "We identified anti-LGi1 and anti-NMDAR encephalitis as most common causes in our cohort." (PMID 30524441, 2018). "Bradyarrhythmia has recently been described as a distinctive prodrome of voltage-gated potassium channel complex/leucine-rich glioma inactivated 1 antibody encephalitis (VGKC/LGI1–ab) leading to pacemaker implantation in 3 cases, just as in one of our patients." (PMID 30687213, 2018). "On the premise that a case has no ethical problem, biopsy or autopsy of basal ganglia and hippocampus at bilateral hemispheres in the patient with LGI1-antibody encephalitis would be critical to verify the hypothesis." (PMID 30253786, 2018). "In addition, our data showed that almost all the patients with LGI1-antibody encephalitis who showed asymmetry in the FDG-PET images, except one, had increased FDG uptake in the hippocampus on the contralateral side of their handedness." (PMID 30253786, 2018). "Eight patients (five males and three females; mean age, 63.4) with LGI1 antibody encephalitis who were diagnosed and treated in the Department of Neurology of Shengjing Hospital of China Medical University from September 2016 to June 2017 were recruited for the current study." (PMID 29980179, 2018).
encephalitis (continued). "Therefore, if LGI1 antibody encephalitis is suspected, routine serum tests for autoimmune encephalitis antibodies are first performed, thus occasionally negating the need for invasive lumbar punctures." (PMID 29980179, 2018). "In combination with clinical manifestations, laboratory tests, and imaging examinations, the diagnosis of LGI1 antibody encephalitis is usually correct; however, it should be noted that increased LGI1 antibody titers were also found in a pathologically confirmed CJD case." (PMID 29980179, 2018). "Recent studies have also deepened the understanding of LGI1 antibody encephalitis." (PMID 29980179, 2018). "As LGI1-antibody encephalitis brains show complement deposition, LGI1-IgG subclasses were assessed." (PMID 29272336, 2018). "LGI1-encephalitis is exceptional and often shows normal CSF findings." (PMID 30233481, 2018). "Additionally, an in vitro study showed that anti-LGI1 from encephalitis patients blocked the binding of LGI1 to ADAM22 by neutralizing the ADAM22-binding domain of LGI1." (PMID 28725222, 2017). "Recovery from LGI1 antibody encephalitis can be protracted and may require multiple immunotherapies." (PMID 28363946, 2017). "Therefore, unilateral basalganglia T1 hyperintensity is an important marker for anti-LGI1 encephalitis withFDBS." (PMID 29213481, 2016). "Thus far, we recommend testing both serum and CSF becausethe most recent studies of patients with anti-LGI1 encephalitis have shownconflicting data." (PMID 29213481, 2016). "In particular, the symptom combination of neuropsychiatric abnormalities and generalized seizures is distinct from that of other types of autoimmune encephalitis, such as anti-LGI1 encephalitis, in which neuropsychiatric symptoms are less common and mild and predominantly focal seizures occur." (PMID 26622479, 2015). "Additionally, to evaluate the model’s predictive efficacy for severe AE associated with different antibody types, external validation was conducted separately on the 109 cases of anti-NMDAR encephalitis and 48 cases of anti-LGI1 encephalitis included in this study." (PMID 40170898, 2025). "Notably, these changes imply that the HYP may influence emotional, cognitive, and sleep‐related symptoms during the acute phase of anti‐LGI1 encephalitis via mechanisms such as behavioral regulation and sleep‐wake cycle control." (PMID 41399525, 2025). "Therefore, the patient was diagnosed with anti-LGI1 antibody encephalitis." (PMID 41019070, 2025). "While anti-LGI1 and anti-CASPR2 antibody encephalitis may be associated with thymoma." (PMID 40170898, 2025). "Although previous case reports or small-sample studies have suggested that patients with anti-LGI1 encephalitis may experience cardiac or metabolic complications, the specific prevalence rates of HHCY and electrocardiographic abnormalities have not been widely quantified." (PMID 41473232, 2025). "Therefore, ictal cold shiver may serve as a significant indicator for the diagnosis of anti-LGI1 encephalitis." (PMID 40958893, 2025). "Additionally, COVID-19-related encephalitis exhibited significant differences in clinical symptoms and CSF white blood cell counts compared with NMDAR-antibody encephalitis; however, it showed limited differences compared with LGI1-antibody and GABAB-antibody encephalitis." (PMID 38772979, 2024). "Finally, it was confirmed as a diagnosis of anti-LGI1 encephalitis." (PMID 37304289, 2023). "Furthermore, we provide a summary of 25 pediatric cases of anti-LGI1 encephalitis." (PMID 37391712, 2023). "In addition, faciobrachial dystonic seizures (FBDS) only appeared in anti-LGI1 encephalitis." (PMID 38152405, 2023). "However, the percentage of CD19 + B cells was higher in the LGI1 encephalitis cases than in HDs." (PMID 37644514, 2023). "In addition, we investigated whether methylation alterations in the promoters of these 13 microRNAs affected their expression in exosomes from patients with LGI1 encephalitis and HDs." (PMID 37644514, 2023).